MDM4 (MDM4 regulator of p53)
Diseases named in the same sentence as MDM4 in open-access papers (continued):
Sharing a sentence is not in itself a finding about the gene and the disease.
melanoma (continued). "For example, high expression of MDM4-A (one of MDM4 isoforms) in human melanoma samples is correlated with poor prognosis, while high MDM4-ALT2 expression in rhabdomyosarcoma likely foreshadows an increased risk of metastasis." (PMID 38281029, 2024). "MDM4-A has been previously discovered to be oncogenic, further highlighting the importance and consideration of MDM4 isoform expression in melanomas and inhibitor development." (PMID 39273363, 2024). "For an overview of the MDM4 isoform expression in the melanoma tumor samples, RT-PCR was performed using primers spanning novel exon junctions in each isoform." (PMID 39273363, 2024). "Alongside this, the alternative splicing of MDM4 also plays a key role in melanomas due to the possible oncogenic roles of its isoforms." (PMID 39273363, 2024). "The current study utilized RT-PCR, RT-qPCR, and long-read nanopore sequencing for the investigation of MDM4 isoforms expressed in malignant melanoma tissue samples." (PMID 39273363, 2024). "Our data provide some evidence for sex-specific associations of MDM4-rs4245739 and MDM2-rs2279744 (SNP309) with melanoma risk and survival, respectively." (PMID 37345045, 2023). "Our results suggest that MDM4/MDM2 variants are associated with the development of subsequent primaries and with the death of melanoma in a sex-dependent manner." (PMID 37345045, 2023). "Borderline significance was identified for the interaction between MDM4 rs4245739 * MDM2 rs117039649 on melanoma-specific survival (Pinteraction 0.14)." (PMID 37345045, 2023). "To identify credible SNPs responsible for, or contributing to, the effect of the tested MDM2/MDM4 SNPs on melanoma, we mined public databases." (PMID 37345045, 2023). "The in vitro and in vivo induction of MDM4 exon 6 skipping using an antisense oligonucleotide have been reported to inhibit MDM4 protein abundance and melanoma growth and to increase sensitivity to MAPK-targeting therapeutics." (PMID 37875914, 2023). "MDM4-S is produced as a result of MDM4 exon 6 skipping, and plays critical roles in inhibiting proliferation of melanoma." (PMID 35365208, 2022). "ASO-mediated exon 6 skipping of MDM4 reduces the amount of full-length MDM4 and inhibits melanoma cell growth." (PMID 36271053, 2022). "In melanoma, alternative splicing of MDM4 mRNA is regulated by serine/arginine-rich splicing factor 3 (SRSF3), which belongs to the SR protein family of splicing factors." (PMID 34144037, 2021). "When compared to data from short-term cultures of human melanomas, the pattern of MDM4 isoform expression is dramatically different." (PMID 34697572, 2021). "The observed increase of MDM4 in locally induced melanoma tumors is in line with its previous description as a direct miR-150 target gene." (PMID 33228711, 2020).
melanoma (continued). "Clinically used fluoroquinolone antibiotics were recently reported to induce a switch in MDM4 mRNA splicing, and benzimidazole anthelmintics inhibited MDM4 expression in melanoma cells, indicating opportunities for drug repositioning." (PMID 32934219, 2020). "MDM4 overexpression renders most primary melanoma cultures relatively immune to specific MDM2 inhibition." (PMID 31374895, 2019). "In normal adult melanocytes, a decay-targeted isoform of MDM4 (MDM4-S) is produced; in melanoma cells, enhanced exon 6 inclusion leads to the expression of full-length MDM4." (PMID 29156643, 2017). "More recent studies have clarified the molecular mechanisms responsible for MDM4 overexpression in melanoma, mainly related to an alternative splicing switch." (PMID 29156643, 2017). "Mechanistically, some SR proteins may be involved in regulating MDM4 splicing variants; however, SRSF3 is one of the most essential enhancers of exon 6 in melanoma cells." (PMID 38462618, 2024). "This inactivity can be attributed, in part, to the frequent overexpression of MDM4 in melanomas." (PMID 39273363, 2024). "The current study both identifies and quantifies MDM4 isoforms present in melanoma tumor samples." (PMID 39273363, 2024). "The in-depth relationship of miR-191 binding and MDM4 in relation to melanoma development remains to be elucidated, adding in some way to the inconclusive research on the role of hormonal and reproductive factors in melanoma to date." (PMID 37345045, 2023). "Formal analyses demonstrated that females, but not males, who carried the variant MDM4-rs4245739*C were more likely to develop a new primary melanoma, and those with the variant MDM2-rs2279744*G were less likely to succumb to the disease." (PMID 37345045, 2023). "We observed that MDM4 is amplified in melanomas, more so than the related protein MDM2." (PMID 34697572, 2021). "On the contrary, MDM4 overexpression is observed in many cancers, including melanomas." (PMID 34697572, 2021). "The splicing enhancer SRSF3 is necessary for the generation of MDM4-FL in melanoma cells." (PMID 34144037, 2021). "As MDM4 is overexpressed in additional types of cancer, this strategy may be applicable beyond melanoma." (PMID 34771719, 2021). "In melanoma, more than 65 % of tumors express high MDM4 levels." (PMID 32934219, 2020).
melanoma (continued). "Already a drug exists that through its inhibition of MDM4 makes melanoma much more treatable." (PMID 23303309, 2013). "Interestingly, previous studies showed that Mdm2 and Mdm4 are highly expressed in melanoma." (PMID 39857778, 2025). "Interestingly, overexpression of MDM4 in glioma and melanoma mouse models led to enhanced tumorigenesis and blocked the effectiveness of chemotherapies, all suggesting that MDM4 may be oncogenic and lead to chemotherapy resistance in vivo." (PMID 33536467, 2021). "However, MDM4 was found weakly expressed in mutant BRAF vemurafenib-resistant melanoma cell lines." (PMID 31374895, 2019). "Interestingly, in human melanoma cell lines and in melanoma patient-derived xenograft mouse models, antisense oligonucleotide-mediated skipping of exon 6 decreased MDM4 levels, inhibited melanoma growth, and enhanced sensitivity to various anti-melanoma therapeutics." (PMID 29156643, 2017). "Preliminary studies from this laboratory determined MDM4-A to be the most commonly expressed alternative transcript of MDM4 in melanomas through TCGA data, the Patient-Derived Model Database (PDMDB), and RT-PCR of melanoma and nevi samples." (PMID 39273363, 2024). "Specifically, MDM4 was nominated by long-range chromatin interaction (locus 4, signal 4, ~550 kb) and was further nominated by melanocyte MWAS and TCGA melanoma TWAS analyses." (PMID 39802764, 2024). "In this study, treatment of melanoma cells with palbociclib resulted in suppression of PRMT5 activity, which altered pre-mRNA splicing of MDM4 and downregulated MDM4 protein levels." (PMID 37502925, 2023). "Hence, we experimented with melanoma A375 cells, and our results showed that treatment with MMRi62 for 24 h induced MDM4 downregulation in a concentration-dependent manner; furthermore, we observed that this activity could be rescued by using a 1 μM bortezomib treatment for 16 h before cell harvest." (PMID 35992795, 2022).
melanoma (continued). "The aim of this study was to check possible correlations between hyperprogression to checkpoint inhibitors and amplification (≥4 copies) of MDM2, MDM4 or EGFR in acral and mucosal melanoma." (PMID 32110946, 2020). "ASO-mediated exclusion of MDM4 exon 6 leads to a decrease in MDM4 abundance through the AS-NMD pathway, which enhances the drug sensitivity and apoptosis of melanoma cells." (PMID 29283381, 2017). "Recently, MDM4 over MDM2 has been shown to be overexpressed in cells freshly isolated from primary and metastatic melanomas compared to cultured melanoma cell lines, the later being likely selected for MDM2 overexpression." (PMID 24416617, 2013). "Interestingly, MDM4 is overexpressed in ~65% of cutaneous melanomas, whereas MDM2 has lower levels of upregulation in melanomas." (PMID 39273363, 2024). "Specifically, females, but not men, with the MDM4 rs4245739*C allele were more likely to develop multiple primaries, and those with the MDM2 SNP309*G allele were less likely to succumb to melanoma compared with those carrying the C allele." (PMID 37345045, 2023). "Despite the importance of MDM4 in melanoma, however, there has never been a systematic study of which transcripts are present in human melanomas." (PMID 34697572, 2021). "Demonstration of increased levels of MDM4 protein, independent of gene amplification, was a groundbreaking discovery that was demonstrated initially in melanoma." (PMID 30689920, 2019). "rs12119098 is not an eQTL for MDM4 (P = 0.10) or any other gene in melanoma tumors." (PMID 39802764, 2024). "However, higher total expression of MDM4 did not correlate with melanoma patient survival in these TCGA data." (PMID 34697572, 2021). "In line with this, we found gene amplifications of MDM2 and MDM4 in 26% and of CDK4/6 in 13% of the melanoma biopsies of patients that did not respond to ICB." (PMID 32165639, 2020).
retinoblastoma (50 papers, 2008 to 2025). A malignant tumor that originates in the nuclear layer of the retina. "The polymorphisms of MDM4 and increased expression of MDM4 protein promote retinoblastoma in mice and human." (PMID 35456484, 2022). "In contrast, retinoblastoma is linked to increased MDM4 levels that arise through protection from miR-191 targeting." (PMID 30689920, 2019). "For example, the SNP rs4245739 in MDM4 is significantly associated with ovarian cancer, retinoblastoma and breast cancer." (PMID 30038284, 2018). "To explore the MDM4 transcript variants in retinoblastoma, we performed transcriptome sequencing on 3 primary retinoblastomas that were used to generate the xenografts in this study (SJ39, SJ41, and SJ42)." (PMID 22916154, 2012). "In a very small cohort of retinoblastoma samples, there was an association between MDM4 gain and increased mRNA and protein expression." (PMID 22916154, 2012). "In some retinoblastoma patient samples, the capacity of miR-191 to engage MDM4 mRNA is eliminated by somatic mutations (SNPs) that eliminate this miR binding site (as discussed in Section ‘MDM4 SNPs and cancer risk.’); while in others miR-191 levels are lower than in the normal fetal retinae." (PMID 30689920, 2019). "The transcriptome analysis showed that all of the transcripts expressed in the 3 retinoblastoma samples that were used to generate the orthotopic xenografts had the A/A allele of MDM4 SNP34091 which is the allele that is believed to be less sensitive to regulation by miR-191." (PMID 22916154, 2012). "This group and others also showed that miR-191 could selectively bind to MDM4-C allele mRNA but not MDM4-A allele mRNA, which resulting in a statistically significant increased expression of MDM4 mRNA and protein levels among MDM4 rs4245739 A allele carriers in ovarian cancer and retinoblastoma." (PMID 23724042, 2013). "However, we could not establish a statistically significant association between SNP34091 genotype and retinoblastoma susceptibility or MDM4 gene expression levels because of the relatively low proportion of MDM4 SNP34091 C/C allele in our cohort." (PMID 22916154, 2012). "Copy-number gain of MDM4 has been identified in approximately 65% of retinoblastoma cases, correlating with elevated transcript and protein levels." (PMID 41465072, 2025).